EGFR (epidermal growth factor receptor)
Diseases named in the same sentence as EGFR in open-access papers (continued):
Sharing a sentence is not in itself a finding about the gene and the disease.
tumor (continued). "It uses antibodies against specific tumor antigens (HER2, EGFR), but also mesenchymal markers." (PMID 36362369, 2022). "In comparison, without LIGHT expression, anti-EGFR treatment was similar to BATs treatment on HT29 tumor volume." (PMID 35177811, 2022). "Dysregulated EGFR/MAPK signaling pathway has been reported in a variety of human cancers mainly because it can lead to malignant transformation and tumor progression through increased cell proliferation, prolonged survival, angiogenesis, anti-apoptosis, invasion, and metastasis." (PMID 35463300, 2022). "In contrast to our findings from the tumour immune infiltrate, we found that Ki67 levels were not altered upon EGFR inhibition compared to vehicle control in spleen tissues." (PMID 36010935, 2022). "RT-qPCR of these cells reflected a similar trend to that observed in the uptake assay, with EGFR-targeted miR-125b ASO-loaded EVs resulting in significantly higher knockdown only in tumor cells, but not in lung cells." (PMID 35547755, 2022). "These were directed against tumor associated antigens such as human epidermal growth factor receptor (EGFR), epithelial cell adhesion molecule (EpCAM) and human epithelial growth factor receptor 2 (HER2), thereby retargeting Ovs to recognize a variety of tumor cell types." (PMID 35965554, 2022). "We examined an EGFR exon 19-deleted LU5221 PDX model and observed that upfront combinations with osimertinib and AURKB inhibitor AZD2811 (25 mg/kg) or sequential combination delayed tumor regrowth relative to monotherapy." (PMID 36575215, 2022). "We found inhibition of DDR1/BCR signaling with EGFR/ERBB2 to be effective independent of KRAS mutation type and status in COAD and additional primary tumor model of GBM." (PMID 35664781, 2022). "The inhibition of both EGFR (TKI) and PFKFB3 (PFK158) enhanced anti-tumor efficacy in NSCLC." (PMID 36532721, 2022). "Moreover, enhanced tumor growth through upregulation of the epidermal growth factor receptor (EGFR) and cancer cell survival through interaction with phosphatidylinositol 3-kinase/(PI3K)/AKT also trigger tumor progression." (PMID 35203404, 2022). "Analysis of publicly available data regarding putative drug sensitivity of tumour cells in direct correlation to USP28 expression scored the PIK3, EGFR and MAPK pathway as top hits, which directly confirmed our experimental data regarding USP28 expression relative to oncogenic drivers." (PMID 35364627, 2022). "Comparison of EGFR L858R, EGFR exon 20 insertion, KRAS mutation, histological type, and tumor grade between smoker and non-smoker in different gender, and between male and female patients in smokers or non-smokers." (PMID 35061839, 2022). "Previous studies confirmed that FAM83A-AS1 could promote the expression of intracellular FAM83A and thus confers tumor cells with EGFR-TKI resistance, indicating that targeting FAM83A-AS1 might have the potential to reverse EGFR-TKI resistance in LUAD." (PMID 35002507, 2022). "Long-term EGFR TKI administration has been suggested to induce an intrinsic interferon response in tumor cells, which may improve the tumor microenvironment (TME) by increasing T-cell infiltration that contributes to the treatment response." (PMID 36082280, 2022). "Furthermore, we found slightly increased EGFR and drastically increased IGF1R expression on tumor cell surface after elevating the glucose concentration in the cell culture medium." (PMID 35574343, 2022).
tumor (continued). "In NSCLC, upon M3-mediated EGFR transactivation, the signaling pathway was activated, thus phosphorylating ERK1/2 and AKT, and, under a muscarinic antagonist (R2-8018), the PI3K/AKT and MEK/ERK1/2 pathways were inhibited, therefore, inhibiting tumor growth." (PMID 35565451, 2022). "Considering the target, EGFR-vIII is a tumor-specific antigen that is absent in normal tissues; this syndrome is unlikely attributed to the off-target toxicity." (PMID 35874698, 2022). "As well, on the side of TAMs that are educated by EZH2 inhibitor-treated BC cells, the increased IL-10 secretion stimulates EGFR-SRC signaling to enhance cell motility and the increased VEGF secretion accelerates vasculature development, which contribute to tumor metastasis all together." (PMID 36038549, 2022). "HPV-positive tumours showed downregulated MAPK, Estrogen, EGFR, TGFbeta, WNT signaling activity." (PMID 35954409, 2022). "Taken together, these results suggested that a ferroptosis inducer could enhance cisplatin-mediated ferroptosis of EGFR-MT NSCLC cells, thereby promoting the anti-tumor immune response of ICI therapy." (PMID 35784745, 2022). "In addition to EGFR, IL-6 signaling also activates STAT3, and IL6R blockade significantly inhibits tumor progression." (PMID 36010693, 2022). "The mu-αEGFR-172 ADC failed to inhibit tumor growth or improve mouse survival when the B16F10 cell line did not express human EGFR." (PMID 36442099, 2022). "The BIBW2992, also known as afatinib, is a second-generation tyrosine kinase inhibitor (TKI) that could target EGFR and HER2 molecules, resulting in tumor suppression." (PMID 35967375, 2022). "Indeed, multiple (pre)clinical studies have demonstrated promising results, showing that combining EGFR and PI3K pathway inhibitors often leads to superior anti-tumor effects compared to either treatment alone." (PMID 36551613, 2022). "The results of this study demonstrated that tumor sidedness has no significant impact on treatment outcomes in KRASwt mCRC patients treated with anti-EGFR Ab in second- or later-line treatment." (PMID 35242708, 2022). "We observed decreased tumor cell proliferation in the lungs of gefitinib-treated mice challenged with DARPP-32-silenced HCC287GR cells, confirming that DARPP-32 knockdown enhances EGFR TKI-induced anti-cancer effects in gefitinib-resistant tumors in vivo." (PMID 34675407, 2022). "We speculate that EGFR-TKIs and PD-1/PD-L1 inhibitors block PI3K/AKT/mTOR signaling, which blocks the absorption of essential amino acids by tumor cells, resulting in increased phenylalanine, n-acetyl-l-leucine, and n-acetyl-d-tryptophan." (PMID 36034789, 2022). "Interestingly, the downregulation of STYK1 alone also compromised colony growth similarly to the EGFR TKI, indicating that STYK1 acts as a tumor-promoting factor in EGFR-mutant cells." (PMID 35840561, 2022). "In EGFR TKI-resistant tumor xenografts, the expression level of AXL was found to be elevated, and inhibition of AXL recovered the sensitivity to EGFR-TKI, which implies that activation of AXL is essential for acquired resistance to EGFR-TKI in NSCLC." (PMID 35805163, 2022). "We then checked if EGFR and CXCR4 in sEVs derived from serum could act as tumor detection biomarkers for NSCLC." (PMID 35269297, 2022). "Several targeted therapies have been approved for the treatment of NSCLC harboring certain genetic variations in EGFR, ALK, ROS1, or BRAF and it is required to determine the existence of those genetic variations in tumor before targeted therapies are given to patients." (PMID 35061839, 2022). "Among them, IGF1R and EGFR can activate PI3K/AKT and MEK/ERK signaling pathways, respectively, to enhance tumor progression and drug resistance, and YY1 activates Wnt/β-catenin signaling by promoting CTNNB1 expression to promote tumor growth." (PMID 36131281, 2022).
tumor (continued). "There was a relatively large proportion of patients with unknown EGFR, ALK and ROS1 status in both cohorts and the tumour PD-L1 expression was unknown for many patients in the Post-1L IO cohort." (PMID 36139641, 2022). "Heteronemin combined with tetrac appeared to reduce the expression level of signal transduction pathways involved in EGFR signaling, which includes cell proliferation, angiogenesis, and epithelial–mesenchymal transition (EMT) in tumor metastasis compared to heteronemin alone." (PMID 36005485, 2022). "Inhibiting EGFR signaling restores the expression of major histocompatibility complex (MHC) molecules, and enhances secretion of interferon-gamma (IFNγ) which increases PD-L1 expression on tumor and immune cells within the tumor microenvironment (TME)." (PMID 35372020, 2022). "The susceptibility of some of the erlotinib conjugates to react to the light-activated oxidative process by a degrading process deliberating product(s) with erlotinib properties indicates a non-anticipated benefit for PDT of EGFR signal-dependent tumor." (PMID 36232384, 2022). "Immunohistochemical staining of tumor sections revealed the presence of specific staining of EGFR on the M3-EGFR mouse tumor, while no staining was seen on the original M3 mouse tumor." (PMID 36432639, 2022). "Of note, these antibodies did not confer further benefits even when they were combined with MIT (p > 0.05), implying basically independence of PC3 tumor growth on the EGF/EGFR axis, specifically in the absence of stromal cells." (PMID 36202915, 2022). "The EGFR inhibitor gefitinib enhances the efficacy of PD-1 monoclonal antibody by reducing the interaction between PD-L1 and PD-1, enhancing IL-2 expression in T cells, promoting the activation of CD8+ TILs and improving T cell-mediated tumor cell killing." (PMID 36612100, 2022). "Because the Arp2/3 components were crucial for WASH function during tumor-suppressive cell competition, we examined whether WASH may impact on EGFR signaling through regulating endosomal actin polymerization." (PMID 36271083, 2022). "In the event that a tumour type does not express EGFR for example liver cancer, which expresses asialoglycoprotein, then the bispecific antibody can be changed to anti‐asialoglycoprotein while the anti‐O‐polysaccharide component remains constant." (PMID 34665932, 2022). "Despite EGFR inhibitors having dramatically improved the survival outcomes and quality of life of EGFR-positive NSCLC patients, drug-resistance mechanisms invariably emerge after treatment, leading to tumor progression within 2 years." (PMID 36139605, 2022). "Although EGFR expression colocalized with fluorescence signal, tumor regions without EGFR expression also showed high fluorescence, suggesting that a tumor-specific fluorescence signal is not mediated only by EGFR expression." (PMID 34531264, 2022). "A randomized phase III study comparing EGFR-TKI and surgery with EGFR-TKI alone is needed to verify whether the early tumor resection may increase survival." (PMID 36581631, 2022). "Together, these data reveal that EGFR inhibition appears to modulate T-cells specifically in the TME towards an enhanced proliferative and inflammatory phenotype, thus facilitating an improved T-cell response against the tumours." (PMID 36010935, 2022). "Indeed, it was effective in all tumour subtypes, including those overexpressing HER2, a tyrosine kinase receptor from the same family as that with which EGFR can heterodimerize." (PMID 36380366, 2022). "When EGFR binds to its ligands, it activates the PI3K/Akt pathway, promotes the growth and proliferation of tumor cells, inhibits apoptosis, promotes invasion and metastasis, and regulates tumor angiogenesis." (PMID 36387129, 2022). "MET-targeted therapies using repurposed inhibitors have met with some initial success in the clinic; however, unlike cancers driven by other oncogenes such as EGFR, response rates in METΔex14 mutant tumours are lower." (PMID 35326531, 2022).
tumor (continued). "Immunohistochemistry (IHC) staining was thought to be unreliable for the quantification of EGFR for multiple reasons such as tumor heterogeneity, lack of sensitivity in the detection system, and challenges in attaining the sample." (PMID 35455447, 2022). "Eligible patients had untreated advanced nonsquamous NSCLC with a high tumor mutational burden (TMB) (tissue TMB >10 mutations per megabase or blood TMB ≥1.54 mutations per megabase) and without sensitizing EGFR or ALK alterations." (PMID 35498381, 2022). "The EGFR pathway is involved in the regulation of ABCG2 expression and function; in fact, EGFR inhibition led to the reversal of ABCG2-mediated chemoresistance in in vitro and tumor models." (PMID 35163586, 2022). "In patients experiencing an oligoprogression after a durable response to EGFR-TKI, the strategy to maintain the inhibition of EGFR inhibitor-sensitive clones, to avoid the potential subsequent rebound tumor flare and symptomatic progression, is frequently used in clinical practice." (PMID 35159099, 2022). "CGA inhibited EGFR/PI3K/mTOR, HIF, VEGF pathways and MAPK/ERK pathway that may suppress tumor cell growth." (PMID 36386222, 2022). "Addition of aggregated CaP-NPs to NK-tumor co-cultures still allowed the induction of substantial antibody-dependent cellular cytotoxicity (ADCC), which, in our experimental system, was induced by anti-EGFR antibody." (PMID 35251021, 2022). "This work provides the structural basis for the use of EgB4 as a research tool, for targeting of drugs such as nanobody-drug conjugates, and as biomarker to monitor EGFR expression in tissues and tumor imaging, while not affecting EGFR function." (PMID 35232398, 2022). "When blood samples from healthy donors were analyzed with the Attune CytPix, EpCAM+EGFR+ events showed no tumor cell-like morphology." (PMID 36613466, 2022). "Enhanced EGFR signaling may promote a strong activation of ERK and pEMT via SLUG in HNSCC, preferentially at the tumor margin." (PMID 34382739, 2022). "Previous studies have shown that, although immunotherapy approaches such as targeting immune checkpoint by ICB are beneficial in many cancer entities to promote a proinflammatory TME, EGFR-driven NSCLC tumours do not respond to this type of therapy." (PMID 36010935, 2022). "Thus, identifying a suitable tyrosine kinase inhibitor (TKI) with multiple functions in modulating the EGFR, KRAS, and mTOR pathways is important to reprogram tumor metabolism and reverse mitochondrial dysfunction." (PMID 36145507, 2022). "This was especially true in patients with HER2E-type tumor or those negative for EGFR/HER1 and/or positive for HER3 or HER4." (PMID 35505646, 2022). "After PSM, 53 EGFR-TKI-treated patients who received tumor resection and 53 patients with no tumor resection were analyzed." (PMID 36581631, 2022). "GYP significantly reduced the expression of STAT3, EGFR, TYMS and MAPK14 in tumor tissues, while cisplatin combined with GYP could further reduce the expression of STAT3, TYMS and MAPK14 in tumor tissues." (PMID 36532716, 2022). "By simultaneous binding of EGFR and PD-L1, HCP-LCE might exhibit elevated tumor-selectivity, which could reduce side effects." (PMID 35479092, 2022). "The EGFR/Her2 inhibitors afatinib and neratinib were not potent in B1/P/Rbf tumor cells despite amplification and upregulation of Her2, indicating downstream activation of the pathway." (PMID 36333737, 2022). "In many tumor types, the SHH signaling pathway has been reported to crosstalk with other critical molecular signaling pathways involved in cancer, such as RAS/RAF/MEK/ERK, PI3K/AKT/mTOR, EGFR, and Notch." (PMID 36034794, 2022). "CAF-mediated non-cell-autonomous adaptive resistance to MET- and EGFR-targeted therapies in lung cancers via a metabolic shift involving paracrine crosstalk between tumor cells under drug exposure and their surrounding CAFs has been reported." (PMID 35326670, 2022).
tumor (continued). "In vitro studies revealed that EGFR-targeted CAR-T cells exhibit specific cytolytic activity and produce high levels of cytokine (IL-2, IL-4, IL-10, TNF-α, and interferon-γ [IFN-γ]) against EGFR-positive tumor cells." (PMID 35720364, 2022). "In other words, significant difference was merely observed in tumor size between tumor lesions with positive EGFR expression and those with negative expression, with larger size found in lesions with positive expression." (PMID 36591483, 2022). "In the cancer milieu, decorin signals through EGFR and Met receptors found on the surface of cancer cells, effectively resulting in decreased HIF-1α and marked angiostasis of the tumour vasculature, suppression of tumour growth and enhanced mitophagy." (PMID 34982945, 2022). "However, the anti-tumor efficacy of TKIs varies greatly across individual patients, and correspondingly the PFS of patients treated with EGFR-TKIs ranges from several months to several years." (PMID 36503478, 2022). "Molecular genetic testing showed that the tumor cells lacked IDH gene mutations, LOH of 1p/19q, MYCN amplification, and EGFR alteration." (PMID 35663322, 2022). "Intriguingly, despite high expression of EGFR on healthy donor HDF cells, we observed obvious and significant decrease in in vitro HDF killing by hinge-truncated EGFR-sdCAR-T cells and increased selectivity for SKOV3 tumor cell killing." (PMID 35935988, 2022). "Baseline characteristics across sintilimab, pembrolizumab, atezolizumab, and nivolumab registration studies in the first-line treatment of nonsquamous NSCLC without EGFR or ALK genomic tumor aberrations." (PMID 35756655, 2022). "For example, the tumour suppressor and stem cell marker Lrig1 is a negative regulator of the epidermal growth factor receptor (EGFR) family." (PMID 36420140, 2022). "We have studied the tumor-promoting ability of DUSP3 deficiency by examining the onset of LAC in DUSP3 +/+ and DUSP3−/− mice with or without the EGFR-Del Tg gene." (PMID 35705979, 2022). "In fact, in our model, EGFR is an abundantly expressed tumor antigen, whilst Sellmyer and colleagues used GD2 for targeting which is expressed heterogeneously and at relatively low levels in tumor cells." (PMID 35836798, 2022). "In EGFR-mutant NSCLC patients, the genotyping of CTCs and tumor biopsies gave comparable results." (PMID 35326725, 2022). "High frequency of genetic alterations of tumor suppressors (e.g., PTEN and CDKN2A/CDKN2B) and oncogenes (e.g., PDGFA and EGFR) suggested that these cancer driver genes might be responsible for initiation of mGBM but not contribute to the progression of mGBM." (PMID 34987659, 2022). "A link with an inflammatory and tumor-promoting pathway in HCC cells was suggested and a communication possible is due to the induction of amphiregulin by TNF-alpha, allowing the transactivation of EGFR." (PMID 35565451, 2022). "EGFR-positive tumor cells were dense in HGG (3,000 ± 450 cells/mm2) and HNSCC (2,100 ± 180 cells/mm2) but sporadic in LAC (1,300 ± 100 cells/mm2), with fewer than 10 cells occupying over 50% of tumor areas." (PMID 35332092, 2022). "In a xenograft mouse model of EGFR-mutated NSCLC, neither anti–PD-L1 nor anti-CD73 antibody alone inhibited tumor growth compared with the isotype control." (PMID 35132961, 2022). "Tumor cells with low EGFR expression were not phagocytosed, even when high anti-EGFR mAb concentrations were added." (PMID 35035479, 2022). "Our bispecific mAb may be used to target human EGFR-positive tumors and locally regulate CD137 signaling in tumor immunotherapy studies." (PMID 35197968, 2022). "Therefore, the antiapoptotic EGFR gene was silenced, and meanwhile, the TMZ concentration was heightened, enhancing tumor cell apoptosis." (PMID 35903366, 2022).